CXCR4 (C-X-C motif chemokine receptor 4)
Diseases named in the same sentence as CXCR4 in open-access papers (continued):
Sharing a sentence is not in itself a finding about the gene and the disease.
infection (continued). "Finally, although SCMs allowed CCR5-using viruses to infect CD4−CCR5+ cells, SCMs did not stimulate the infection of CD4−CXCR4+ cells by CXCR4-using viruses." (PMID 19343205, 2009). "This may also explain why X4 has trouble initiating infection when R5 virus is absent: CXCR4's per-cell density on the most crucial memory CD4+ T cell population is simply too low." (PMID 19680436, 2009). "Importantly, coreceptor switch from CCR5 to CXCR4 is less common in subtype C infection, the pathological significance of which, is not understood." (PMID 18328091, 2008). "In contrast, the addition of exogenous CXCR4 in the presence of either the feline CD134 CRD1 chimera (CRD1), or native feline CD134 (CD134) revealed a significantly more marked enhancement of infection with the T271I and Δ2N viruses than with the WT or N342Y viruses." (PMID 18721458, 2008). "The addition of exogenous feline or human CXCR4 alone did not enhance infection of the control cells mediated by either the GL8 or CPG41 Envs significantly, irrespective of whether WT, T271I, N342Y or Δ2N (control)." (PMID 18721458, 2008). "Here, we examine whether or not productive infection by HIV-1 alters the cell surface expression of CXCR4." (PMID 18190699, 2008). "Peptide 3 did not affect CXCR4-dependent infection of Jurkat T cells." (PMID 15807900, 2005). "Since HIV-1 viruses utilizing CCR5 as coreceptor (=R5 viruses) are predominantly transmitted sexually, it was important to test whether PJ can inhibit not only infection by HIV-1 IIIB, a virus utilizing CXCR4 as coreceptor (=X4 virus), but also infection by an R5 virus, HIV-1 BaL." (PMID 15485580, 2004). "Interestingly, although the CXCR4 antagonist alone did not significantly affect bacterial load or mortality during the acute phase of infection compared to the vehicle control, we observed a trend toward improved overall survival when animals were monitored up to day 14 post-infection." (PMID 41451234, 2025). "CCR5 expression levels and activation state may independently affect infection rates; the former by promoting entry of CCR5-tropic HIV, and the latter by increasing the permissiveness of CD4+ T cells to HIV infection, which can affect infection rates of both CXCR4- and CCR5-tropic HIV." (PMID 34899645, 2021). "Therefore, the role of Cxcl12/Cxcr4 signaling axis against infection may be not affected by the retention and/or migration of leukocyte population." (PMID 33013914, 2020). "In fact, the infection and depletion of central memory CD4+ T cells (CD4+ TCM) (that are CCR5 negative and, in the absence of other stimuli, can only be infected by X4 viruses because they do express CXCR4) is hypothesized to contribute to the establishment of chronic immune activation." (PMID 30818365, 2019). "In the context of an infection with Nef-impaired or nef-deleted virus, the impact of some host factors may be altered because of the slower replication kinetics of the virus or because they are not inactivated by Nef, such as tetherin and cell-surface receptors, e.g. CCR5 or CXCR4." (PMID 24928910, 2014). "Thus, it can be hypothesized that the HPAI has an inhibitory effect on the immune response in trachea by an inhibition of the CXCR4 signalling pathway, as compared to the LPAI virus, and then promotes a systemic infection in Muscovy ducks by evading the host immune response." (PMID 24015922, 2013). "To investigate whether the increased stability of the CD4 complex with gp140 contributes to infection with HIV, we compared the effects of cis-expression of DC-SIGN on in vitro infection with HIV-1 IIIB and HIV-1 IIIBx, a variant of IIIB that can bind directly to CXCR4 without CD4." (PMID 22163292, 2011). "Our first report in RAG-hu mice showed a lack of CD4+ T cell loss in the blood through 24 weeks of infection with NLENG1-IRES, a reporter strain of HIV-1 that expresses GFP and places the nef gene under the control of an IRES element in the background of the CXCR4-tropic strain NL4-3." (PMID 21835012, 2011).
infection (continued). "Monocyte chemokine receptors (pre- and post-operative monocyte CXCR4) and receptors involved in antigen presentation (CD80) were the greatest discriminators between patients with and without post-operative infections (loading vector coefficient of > 0.8)." (PMID 38655251, 2024). "While HSPC susceptibility to HIV infection hinges largely on the expression of CD4, CXCR4, and CCR5, CD4-independent infection mechanisms have been described and should not be discounted for infection of HSPCs." (PMID 37497228, 2023). "It is notable that approximately half of the clones from each time point were nonfunctional, i.e., levels of infection were not significantly different from background levels on both U87.CD4.CCR5 and U87.CD4.CXCR4 cell lines (data not shown)." (PMID 35727047, 2022). "The data also showed that MAIT cells expressed more CD69 (gut aGVHD vs. no-event, p = 0.02; gut aGVHD vs. infection or fever, p = 0.011), CXCR3, and CXCR4 in the gut aGVHD group than in the other two groups." (PMID 34539656, 2021). "The lack of infection of H7 cells with CCR5 tropic HIV confirms CCR5 KO as they expressed the HIV receptor CD4 and the co-receptor CXCR4 comparable to WT TZM Cells." (PMID 33516234, 2021). "By assessing the CXCR4, our data showed that reovirus has no devastating effect on migratory potency of infected-MSC, particularly in low MOI infection." (PMID 33933086, 2021). "However, this difference in activation state may not be an important determinant of increased susceptibility of these cells to HIV infection, since infection rates by CCR5-tropic HIV, but not CXCR4-tropic HIV, are enhanced under the T-PBMC stimulation condition." (PMID 34899645, 2021). "Here, we describe the CXCR4 and CD26 expression levels in different lymphocyte subsets of HHT patients with history of severe infection (HSI), in comparison with HHT patients without HSI and with healthy control subjects (HC) matched in age and sex." (PMID 34906163, 2021). "Agonists of CB2, but not CB1, have been shown to reduce infection in primary CD4+ T cells following cell-free and cell-to-cell transmission of CXCR4-tropic virus." (PMID 32471272, 2020). "Transmitter/founder (T/F) viruses are involved in the initial infection, and virtually always use CCR5 rather than CXCR4 and infect T cells but not macrophages." (PMID 30886166, 2019). "In vitro experiments showed that, even in the absence of a productive infection, the HIV-1 gp120 binding to CXCR4 and CCR5 is able to activate HSCs." (PMID 29324755, 2018). "In vitro experiments performed by diverse research groups showed that, even in the absence of a productive infection, the HIV-1 gp120 binding to CXCR4 and CCR5 is able to activate the Hepatic Stellate Cells, thus promoting the fibrogenetic process." (PMID 29324755, 2018). "In fact, inducing anti-CCR5 antibodies in uninfected individuals to prevent the infection rather than to treat the infection is a more rational approach since the therapeutic effect of inhibitors could be bypassed by the emergence of dual-tropic or CXCR4-tropic viruses." (PMID 28484468, 2017). "To determine the stage of the infection block, we infected HALUC-expressing (negative control) or HASUN1-expressing U87MG CD4/CXCR4 cells with the VSV-G-pseudotyped HIV-1 GFP LV and isolated total DNA at various time points postinfection." (PMID 28747499, 2017). "While these strategies are capable of generating cells that are highly resistant to infection with CCR5-using HIV, they offer no protection against viruses that use CXCR4." (PMID 24662607, 2014). "PBMCs treated with prostratin and infected with HIV NL4-3-Luc pseudotyped with VSV envelope were not refractory to infection despite the downregulation of CD4 and CXCR4, confirming that the control of viral replication occurred at entry level." (PMID 24827152, 2014). "hNOJ (IR+) and hNOJ (IR−) mice were highly permissive for infection with both CCR5-tropic HIV-1 and CXCR4-tropic HIV-1 (data not shown)." (PMID 23301078, 2013).
infection (continued). "Although B cells express high levels of CXCR4, treatment with anti-CXCR4 mAb prior to addition of HIV-1 to B cells does not inhibit trans infection of the T cells." (PMID 24278768, 2013). "All the Env variants had a CCR5 tropism as determined by a reduction/ absence of TZM-bl cell infection in the presence of the CCR5 antagonist TAK-779, but not in the presence of the CXCR4 antagonist AMD-3100 (data not shown)." (PMID 23305422, 2013). "It has been known for over two decades that quiescent/resting CD4+ T-cells are highly refractory to HIV-1 infection, particularly to post-entry infection of R5-tropic, but not to X4-tropic viruses since resting CD4+ T-cells express the HIV-1 co-receptor CXCR4." (PMID 23092163, 2012). "In striking contrast, at all times surveyed post infection, almost no CD4T expressing only CCR5 were detected in infected cultures, and the number expressing both CCR5 and CXCR4 was significantly reduced." (PMID 22911696, 2012). "Further, the action of this drug was CXCR4-specific, as JWH-133 treatment was not sufficient to inhibit infection with an isogenic virus that carried a CCR5-tropic Env from molecular clone JRFL." (PMID 22448282, 2012). "We found that agonism of CB2R, but not CB1R, reduced infection in primary CD4+ T cells following cell-free and cell-to-cell transmission of CXCR4-tropic virus." (PMID 22448282, 2012). "As expected, the knockdown of dynamin 2 expression mediated by the siRNAs suppressed the MLV vector infections in mouse NIH3T3, human TE671, and rat XC cells, but not the CXCR4-tropic HIV-1 and VSV infections." (PMID 22022555, 2011). "Immature DCs do not express CXCR4 and allow infection through a CCR5-mediated process (cis infection), which would be in favor of a preferential R5 infection." (PMID 21284900, 2011). "Intrathymic pDC express both CXCR4 and CCR5 and are themselves targets for HIV replication, although it is not known if infection of these cells plays a role in IFN-α secretion." (PMID 20174557, 2010). "All tested molecules inhibited the infection of dendritic cells by CCR5- and CXCR4- tropic NonOps HIV-1." (PMID 20546571, 2010). "A more detailed analysis at day 10 of a primary or secondary infection (data not shown), which revealed a distinct shift in the expression of CD19, MHC class II, CXCR4 and CXCR5 between splenic B220+ cells and CD138+ cells in spleen, blood and bone marrow." (PMID 21124900, 2010). "Since CXCR4+ CCR5- TERT-2 cells appear to harbor R5-tropic HIV-1 BaL more effectively than IIIb, infection appears to be independent of the co-receptor tropism of the HIV envelope protein." (PMID 18637194, 2008). "Can viral clones of subtype C exhibiting expanded coreceptor use make use of other coreceptors on primary cells for infection in the absence of CCR5 and/or CXCR4?" (PMID 18328091, 2008). "This confirms an in vitro study showing an absence of CD4, CXCR4 or CCR5 surface expression and the lack of productive infection by either R5 or X4 virus strains of epithelial cells isolated from normal prostates." (PMID 19117522, 2008). "Control cells expressing endogenous CXCR4 were refractory to infection with all viruses ("endog.") and ectopic expression of CRD1 did not enhance infection ("endog.")." (PMID 18721458, 2008). "Sera from vaccinated military personnel inhibited, and their PBMCs were partially resistant to, infection by HIV-1 strains tropic to CCR5 (R5), but not to CXCR4 (X4), chemokine receptor." (PMID 16965634, 2006). "Although IAV-PR8 infection failed to increase blood neutrophil numbers or CXCL12 expression by endothelial cells, the involvement of the CXCL12/CXCR4 axis in regulating neutrophil, especially LDN, accumulation in the lungs and bone marrow deserves further investigation." (PMID 39773555, 2025). "Furthermore, it has been known since the early 2000s that CXCR4 and CCR5 are present on MPs and can transfer a capacity for infection to cells lacking these receptors." (PMID 38500878, 2024).
infection (continued). "However, unlike knock-out of the CXCR4 or CYPA dependency factors, which resulted in a consistent drop in infection over a 40-fold range of input virus, the effect of CPSF6 knock-out was dose dependent." (PMID 39678349, 2024). "Thus, the high expression of GalCer and CCR5 by jejunal epithelial cells, which express neither CD4 nor CXCR4, would be the basis of the transmission of HIV-1 CCR5 tropic viruses during primo-infection via the mucosal route." (PMID 37511488, 2023). "Similarly, a positive or negative correlation between SDF1 protein levels and CXCR4 expression in CD4+ TL has been observed, which varied according to the stage of infection." (PMID 36902388, 2023). "These interactions may function as receptors of attachment in order to facilitate the infection of target cells negative for CD4 and/or CCR5/CXCR4 coreceptors that are normally responsible for viral entry." (PMID 37511488, 2023). "Interestingly, mAb 717 inhibited infection by SENS, but not RES, viruses, confirming that both viruses do not use the same CXCR4 conformations." (PMID 33872329, 2021). "In order to investigate if either miR-103 or miR-107 influenced steps other than entry in MDMs, mimic-treated macrophages were infected with either CXCR4-tropic or Env-negative HIV-1 that was VSV-G pseudotyped, thus limiting the analysis to a single round of infection." (PMID 32994328, 2020). "No detectable infection in undifferentiated or differentiated THP-1-CD4R cells was obtained using a control, CXCR4-tropic virus (NL4-3-GFP), consistent with the very low levels of CXCR4 expression detected in these cells." (PMID 29301198, 2017). "Additionally, we show that in HCMV, strain TB40E, infected HUVEC the surface expression of CXCR4 is strongly downregulated, whereas in TB40E-delUS28 infected cells, CXCR4 surface expression is not altered in particular at late time points of infection." (PMID 27955674, 2016). "However, we recently identified a transmitted/founder (T/F) virus (ZP6248) that efficiently used an alternative coreceptor GPR15, rather than commonly used CXCR4 and CCR5, to establish clinical infection." (PMID 24897520, 2014). "Furthermore, trans infection mediated by mature DC with R5 but not X4 virus is enhanced by CXCL12, the chemokine ligand for CXCR4." (PMID 24278768, 2013). "The first assumption is likely to be overconservative, given that per-cell CXCR4 density on activated memory CD4+ T cells is lower than on naive CD4+ T cells, so that X4 infection of activated memory CD4+ T cells should not be as efficient as X4 infection of activated naive CD4+ T cells." (PMID 22866173, 2012). "This provides for increased numbers of activated CD4+ T cells for productive infection by X4 virus, but not R5 virus, since activated naive CD4+ T cells exhibit high expression of the CXCR4 chemokine receptor on the cell surface, with no/negligible CCR5 expression." (PMID 22866173, 2012). "We hypothesized that CB2R agonism, like the CXCR4 antagonist AMD3100, would not inhibit viral transfer, but would block productive infection." (PMID 22448282, 2012). "Furthermore, unlike macrophages, infection mediated by CXCR4 alone was equivalent to infection when both coreceptors were present, suggesting no additional contribution of CCR5 in the presence of the CXCR4 pathway." (PMID 21284902, 2011). "However, a superior cytopathicity of CXCR4-using viruses is well demonstrated and results in an accelerated progression to AIDS and death if the infection is not halted by anti-retroviral therapy (ART)." (PMID 21284907, 2011). "However, in vitro the presence of anti-gC1qR mAbs (74,5,2 or 60,11) had no or little impact on the level of infection of purified CD4+ T cells by both CCR5- and CXCR4-tropic HIV strains." (PMID 20617170, 2010).
infection (continued). "These include IL10, Cd55 (complement decay-accelerating factor) and Cxcr4 (CXC chemokine receptor 4), which all have plausible roles in the response to infection but there were no published SNP in exons of any of these and no SNP in conserved intergenic regions." (PMID 21085469, 2010). "Productive infection of T-lymphoblastoid cells by X4 HIV-1 markedly reduces cell-surface expression of CD4, but whether or not the co-receptor CXCR4 is down-regulated has not been conclusively determined." (PMID 18190699, 2008). "However, we cannot rule out that CXCR4+ cells in the prostate are mainly inactivated/naive CD4+T cells and/or CD8+T lymphocytes, both refractory to productive infection." (PMID 19117522, 2008). "Importantly, infection with HIV-1 IND64V (but not HIV-1 EnvVSV) was as efficient in eliciting ATM phosphorylation as HIV-1LAI, both in CD4+CXCR4+ HeLa cells and in CEM cells (not shown)." (PMID 18560558, 2008). "Therefore, a novel compound may not strongly inhibit binding of HIV-1 to CXCR4 or CCR5, but may still exert robust antiviral efficacy and protect against infection through additional predominant or complementary mechanisms." (PMID 35126374, 2021). "Here we confirmed that pulmonary endothelial cells express the HIV chemokine co-receptors CCR5 and CXCR4, which aligns well with the literature and supports the principle that these cells succumb to the cytopathic effects of HIV as pulmonary bystander entities in the absence of infection." (PMID 32678115, 2020). "Regarding CXCR4 expression levels in different subsets, the frequencies of CD34+CD7+CXCR4+ cells in HIV+ samples (mean 2.08 ± 2.56%) were significantly reduced compared to those in HIV− samples (mean 2.49 ± 2.42%), regardless of the degree of infection (data not shown)." (PMID 30761146, 2019). "At day six post infection, Av-5 was significantly more effective against clinical isolate of clade F at 0.4 μM (p = 0.01) Notably, the clade D isolate contained the R5 × 4 tropism, which can enter target lymphocytes using the cofactors CCR5 or CXCR4, rather than just CCR5, like the R5 viral tropism." (PMID 31052477, 2019). "Our findings indicate that heparin can selectively inhibit the productive infection of FIV TCA, but not FIV FS, which is consistent with the report that polyanions (such as heparin and dextran sulfate) selectively inhibit HIV infection of CXCR4+ or CCR5+/CXCR4+ cells, but not CXCR4-/CCR5+ cells." (PMID 25521480, 2014). "The mean fluorescence intensity (MFI) for CXCR4, corresponding to the number of molecules of each receptor on the cell surface, was increased at all timepoints analyzed, whereas the MFI for CXCR7 was increased only at 72 and 96 hours post-infection (data not shown)." (PMID 23116176, 2012).